ALB (albumin)
Diseases named in the same sentence as ALB in open-access papers (continued):
Sharing a sentence is not in itself a finding about the gene and the disease.
atherosclerosis (continued). "Recognizing the critical role of inflammation in atherosclerosis, clinicians frequently utilize markers reflecting inflammation, such as CRP and albumin." (PMID 38673005, 2024). "For example, low serum albumin levels have been observed in individuals with cardiovascular disease, and hypoalbuminemia is considered a potential marker of systemic inflammation and malnutrition, which are factors that may contribute to the progression of atherosclerosis." (PMID 38396639, 2024). "Therefore, we hypothesized that serum albumin levels may be associated with intracranial atherosclerosis, but atherosclerosis was not a good quantifiable indicator." (PMID 37210474, 2023). "According to the PPI network, ALB and AKT1 are the primary targets for Xuefu Zhuyu Decoction therapy to cure atherosclerosis." (PMID 36532728, 2022). "Earlier reports have suggested that inflammation plays a key role in atherosclerosis and confirmed that patients with elevated CRP and lower albumin levels have high occurrence rates of PAD." (PMID 31349820, 2019). "Furthermore CRP and serum albumin can be used in follow-up and determining the prediction of the CAC score and atherosclerosis." (PMID 34445853, 2021). "The MIS was positively correlated with age, the number of hospitalizations, the presence of atherosclerosis, ferritin, IL-6, TNF-α, CRP and MIAS and inversely correlated with the BMI, albumin, prealbumin, hemoglobin, transferrin, creatinine and blood phosphorus." (PMID 33413177, 2021). "Of course, this does not mean the process of increasing urinary albumin excretion, nor other measures of microvascular function as reported here, are truly independent of atherosclerosis." (PMID 20078879, 2010). "NBP can stably bind ALB, ESR1, EGFR, HSP90AA1, and other targets, and may play a role in neuroprotection for patients with DEACMP by modulating Lipid and atherosclerosis, IL-17 signaling pathway, MAPK signaling pathway, FoxO signaling pathway, PI3K/AKT signaling pathway." (PMID 37006490, 2023). "We postulated that the measurement of urinary protein in conjunction with albumin might be helpful for predicting atherosclerosis, especially for non-albuminuric patients." (PMID 31947845, 2020). "The positive correlation between atherosclerosis and inflammation, demonstrated inprevious studies in both general population and hemodialysis patients could also be observed in our study, considering thevariables CRP and serum albumin." (PMID 28443959, 2017).
liver cancer (145 papers, 2009 to 2026). An epithelial or non-epithelial malignant neoplasm that arises from the liver. "An observation of low albumin was found to be indicative of liver cancer risk and, to a lesser extent, myeloma." (PMID 40941010, 2025). "As a cohort study of 82,061 Chinese participants found, ALB level was inversely associated with the incident risk of overall, lung, colorectal, and liver cancer in linear dose-dependent manners." (PMID 38915009, 2024). "Unhealthy sleep was associated with an increased risk of liver cancer, especially in participants with lower ALB levels or higher levels of ALT, AST, TBIL, GGT, ALP, or particularly TP." (PMID 38915009, 2024). "Unhealthy sleep, as well as increased levels of ALT, AST, TBIL, GGT, ALP, and TP and decreased levels of ALB, were significantly associated with increased risk of liver cancer incidence." (PMID 38915009, 2024). "A meta-analysis showed that low levels of pre-albumin were significantly associated with poor prognosis in patients with liver cancer." (PMID 36439435, 2022). "Though there was no previous research exploring the association between albumin and liver cancer risk, it has been confirmed that albumin was produced by hepatocytes and abnormal albumin levels were in relation to hepatic dysfunction." (PMID 34041866, 2021). "With respect to liver cancer risk, we observed an inverse association with albumin levels, and after excluding participants who were diagnosed with cancer within 2 years since enrollment, a more significant association was observed." (PMID 34041866, 2021). "And the significant association between albumin and overall cancer risk is mainly attributed to lung, colorectal and especially, liver cancer." (PMID 34041866, 2021). "Inverse and linear associations were firstly reported between pre‐diagnostic serum albumin and the risks of overall cancer and liver cancer." (PMID 34041866, 2021). "When analyzed by cancer type, the association between albumin and overall cancer risk was mainly attributed to lung, colorectal and especially, liver cancer." (PMID 34041866, 2021). "Although the biological mechanism and clinical importance of serum ALB for the diagnosis and prevention of liver cancers need to be further elucidated, many studies on the association between serum ALB level and cancer risk report differing results depending on the cancer type." (PMID 40186033, 2025). "Similarly, low albumin was associated with an increased risk of cancer with an OR of between 3.2 and 3.8, myeloma (OR between 8.7 and 10.0), and liver cancer (OR between 9.2 and 15.7)." (PMID 40941010, 2025). "Our findings showed that individuals with unhealthy sleep and high levels of ALT, AST, TBIL, GGT, ALP, or TP or low level of ALB had a significantly increased risk of liver cancer incidence compared to those with healthy sleep and low levels of ALT, AST, TBIL, GGT, ALP, or TP or high level of ALB." (PMID 38915009, 2024). "In addition, participants with higher levels of ALT, AST, TBIL, GGT, ALP, or TP or lower levels of ALB tend to have a higher risk of liver cancer incidence." (PMID 38915009, 2024). "Moreover, our study revealed that ALT, AST, TBIL, GGT, ALP, and TP were positively associated with increased risk of liver cancer incidence while the association of ALB was inverse." (PMID 38915009, 2024). "Moreover, a significant inverse linear relationship was observed between serum albumin concentration and liver cancer risk." (PMID 34041866, 2021). "Moreover, high levels of albumin were found to be associated with lung, colorectal, and liver cancer especially among non‐smokers." (PMID 34041866, 2021). "AFP, a glycoprotein belonging to the serum albumin gene family, is commonly utilized as a biomarker for liver cancer." (PMID 41341390, 2025). "A link between high levels of calcium and myeloma incidence was found, in addition to a relationship between low albumin and liver cancer, and low albumin and myeloma." (PMID 40941010, 2025).
liver cancer (continued). "To confirm the hepatic origin of these metastatic lesions, we conducted immunohistochemical staining for liver cancer-related markers (ALB and AFP) with human-specific antigens (human GAPDH and human nuclear antigen) in the metastatic lesions." (PMID 40852642, 2025). "First, missing data regarding key patient characteristics, such as Albumin-Bilirubin grade and Barcelona Clinic Liver Cancer stage, introduce some uncertainty regarding the composition of the pooled patient population." (PMID 40702656, 2025). "The synthesis of albumin constitutes about 50% of the synthesized proteins in the liver, liver cancer impairs the function of liver to synthesize albumin, resulting in a decrease in albumin level." (PMID 39039452, 2024). "The ALBI score, originally used to assess the prognosis of liver cancer patients, includes two indicators: albumin and total bilirubin." (PMID 38191888, 2024). "In the predictive model developed, the Barcelona Clinic Liver Cancer score was the best predictor of mortality, closely followed by the Platelet-Albumin-Bilirubin and Albumin-Bilirubin scores." (PMID 39199720, 2024). "Participants with unhealthy sleep and jointly had lower levels of ALB or higher levels of ALT, AST, TBIL, GGT, ALP, or particularly TP were at higher risk of liver cancer incidence." (PMID 38915009, 2024). "The most substantial relative increase in the risk of liver cancer incidence was observed in individuals with unhealthy sleep and high levels of ALT, AST, TBIL, GGT, ALP, or TP or low levels of ALB." (PMID 38915009, 2024). "A 56-year-old male who suffered from esophageal cancer and liver cancer and received albumin-bound paclitaxel and nedaplatin chemotherapy in combination with Sintilimab immunotherapy appeared swelling along the vessel after infusion of Sintilimab." (PMID 37233405, 2023). "Normally, GPC3 appears in liver cancer and fetal liver, whereas ALB is specifically expressed in the adult liver." (PMID 37017469, 2023). "A Barcelona clinic liver cancer stage 0 (versus B/C) and an albumin-bilirubin grade 1 (versus 2/3) were independent predictors of TO in patients with HCC38." (PMID 36449597, 2022). "Eight patients (42%) had albumin‐bilirubin grade 1, and 18 patients (95%) had Barcelona Clinic Liver Cancer stage B or C. The mean tumor size was 28.5 ± 15.1 mm." (PMID 34105904, 2022). "Progression-free survival (PFS) was consistent through treatment lines, modified albumin–bilirubin (mALBI) grade, Barcelona Clinic for Liver Cancer (BCLC) stage, and α-fetoprotein (AFP) level." (PMID 35740647, 2022). "It is reasonable to combine albumin with γ‐glutamyltransferase,which can reflect the patient's liver function, inflammatory response and immune status to evaluate the prognosis of liver cancer patients." (PMID 35481993, 2022). "Serological tests for alpha-fetoprotein (AFP), alkaline phosphatase (ALP), alanine transferase (ALT), total bilirubin (T-BIL), total protein (TP), albumin (ALB), and hepatitis B surface antigen (HBsAg) are crucial for the diagnosis of liver cancer." (PMID 36425563, 2022). "Due to ALB is produced solely by hepatocytes, we infer that FcRn can more quickly transport ALB to liver cancer cells so that they can proliferate under the pressure of soranfenib." (PMID 34421602, 2021). "Chenodeoxycholic acid and cholic acid have good binding activity with ALB target genes, which can effectively regulate the activity of ALB, so as to improve the treatment status of patients with liver cancer." (PMID 32963562, 2020). "ALB is touted as a liver cancer driver gene as it is significantly enriched with damaging mutations in the European population." (PMID 30521023, 2018). "We treated liver cancer HepG2 cells with 200 mg/L AGEs or bovine serum albumin (BSA) and assayed for cell viability, cell cycle, and apoptosis." (PMID 28816938, 2017).
liver cancer (continued). "Albendazole has been shown to be effective in suppressing liver cancer cells both in vitro and in vivo, and recently has been repurposed for ovarian cancer treatment with a bovine serum albumin-based nanoparticle drug delivery system." (PMID 27716836, 2016). "Furthermore, the observed increase in the levels of in alpha-fetoprotein (a marker for liver cancer) with unaltered albumin levels (a marker for healthy liver function) suggested a potential shift towards a more malignant state." (PMID 41928920, 2026). "In chronic liver disease and primary liver cancer, IDA frequently co-occurs with systemic inflammation and malnutrition, and biomarkers such as albumin, C-reactive protein, neutrophil–lymphocyte ratio, and platelet–lymphocyte ratio are prognostic in both liver cancer and GC." (PMID 41464174, 2025). "Moreover, ALB+KRT7+ epithelium‐derived ALD organoids promote the tumour growth by activating Wnt/β‐catenin signalling of liver cancer cells." (PMID 39834100, 2025). "Experimental studies have also confirmed that in vitro experiments after Pachyman treatment showed that the cellular content of VEGFA protein decreased while the intracellular level of ALB protein increased, ultimately confirming the positive effect of Pachyman on liver cancer." (PMID 39806972, 2025). "Therefore, composite index ratios like the albumin bilirubin score (ALBI) have been increasingly used to evaluate liver cancer prognosis, demonstrating substantial predictive value." (PMID 39421169, 2024). "Previously proposed staging systems for HCC include the Barcelona Clinical Liver Cancer (BCLC) staging, Cancer of the Liver Italian Program (CLIP) score, Japan Integrated Staging (JIS), and Albumin–Bilirubin-TNM of the Liver Cancer Study Group of Japan 6th edition (LCSGJ 6th) (ALBI-T) score." (PMID 37686624, 2023). "It is important to note that adding albumin to immunotoxins may lower the effective dose, as shown in mouse liver cancer xenografts." (PMID 37746282, 2023). "We also identified a proliferative cluster, which mainly consisted of proliferating T cells and a large cluster of HCC cancer cells (40%) expressing both genes associated with normal liver function (ALB, HP, FGA, FGB) and liver cancer (AFP, SPINK1, GPC3, AKR1C1)." (PMID 38030622, 2023). "Albumin level below the cohort median (3.4 g/dL) emerged as an independent risk factor for TTP controlling for AFP > 20 ng/mL as well as Milan, T-stage, and Barcelona Clinic Liver Cancer (BCLC) stage individually." (PMID 35406456, 2022). "Therefore, the substantial reduction in serum albumin and total protein levels observed in Ehrlich solid tumour mice is equal to liver cancer, which reduces biosynthetic efficiency." (PMID 35844382, 2022). "The RCS model suggested an inverse linear association between albumin and the risk of overall cancer (p‐overall < 0.0001, p‐nonlinear = 0.3716) and liver cancer (p‐overall = 0.0002, p‐nonlinear = 0.1807)." (PMID 34041866, 2021). "Given that serum AFP level is a prognostic factor of liver cancer, and neutrophil-to-lymphocyte ratio (NLR) and albumin bilirubin (ALBI) grade are also common indicators for monitoring the prognosis of liver cancer, we used the same method to calculate the AUCs of AFP, NLR and ALBI, respectively." (PMID 33536005, 2021). "The continuous increase in ALB indicates that the liver cancer cells (Huh7-Luci) in the HCC organoid could have functioned normally." (PMID 34439154, 2021). "In addition, the IMF deposition group showed higher AFP, INR, and CP score, and lower sodium and albumin levels, which are markers of the severity of liver cancer." (PMID 31888500, 2019).
liver cancer (continued). "The results of this study suggest that TBIL, PLT and ALB can effectively improve diagnostic efficacy of serum tumor markers for liver cancers but are not the main factors leading to different levels of the diagnostic models between HCC, CCA and benign liver diseases." (PMID 40708828, 2025). "To ask whether the properties of tumor in transplant experiment is the same as the original cell line, we used qPCR to analyse the differentiation-related genes including Afp, Albumin and K19, as well as liver cancer stem cell-related genes such as Prom1, Thy-1, Nanog, and Anpep." (PMID 38956432, 2024). "Individuals with unhealthy sleep and high (≥ median) ALT, AST, TBIL, GGT, ALP, or TP or low (< median) ALB level had the highest HR of 3.65 (2.43–5.48), 4.03 (2.69–6.03), 1.97 (1.40–2.77), 4.69 (2.98–7.37), 2.51 (1.75–3.59), 2.09 (1.51–2.89), or 2.22 (1.55–3.17) for liver cancer, respectively." (PMID 38915009, 2024). "Last but not the least, though our study added to evidence that albumin was significantly associated with total cancer risk as well as risks of lung, colorectal, and liver cancer, the biological plausibility was still moderate and the clinical significance remains to be elucidated." (PMID 34041866, 2021). "There were significant differences between the two groups in sex, history of liver cancer treatment, HCV‐RNA levels, serum albumin levels, AST levels, γ‐GTP levels, creatinine, eGFR, prothrombin activity, platelet counts, and AFP levels." (PMID 41573355, 2026). "Commonly used systems include the albumin–bilirubin (ALBI) score, the Barcelona staging classification (Barcelona Clinic Liver Cancer, BCLC), the Model for End-Stage Liver Disease (MELD), and the model to estimate survival in ambulatory HCC patients (MESIAH)." (PMID 41493845, 2026). "Immunostaining for liver cancer differentiation markers (AFP and ALB) and the proliferation marker (Ki67) demonstrated that the orthotopic PDX tumors of the Liver ECM group showed greater progression compared to those of the Matrigel group." (PMID 40852642, 2025). "The tumor hepatocytes expressed high levels of ALB, AFP, and STAT3, with the later two genes known to be altered in liver cancer and fibrosis, respectively." (PMID 40766612, 2025). "qPCR analysis revealed that the gene expression of liver cancer-specific differentiation markers AFP and ALB was much higher in patient-derived liver cancer organoids (5-fold and 4-fold, respectively) than in normal liver organoids." (PMID 40852642, 2025). "An albumin-glucosamine (AG) lipid complex (LC), composed of stearyl glycyrrhetinate (SG) and DSPE-PEG, is designed to serve as a liver cancer-specific delivery system." (PMID 41624341, 2025). "Such is the case that the new 2022 Barcelona Clinic Liver Cancer (BCLC) classification incorporates Child-Pugh levels, Model for End-stage Liver Disease (MELD), and also incorporates the Albumin-Bilirubin (ALBI) score into patient prognosis." (PMID 39199720, 2024). "Staging systems such as the Barcelona Clinic Liver Cancer (BCLC) evaluate these aspects, along with objective scores like the Model for End-stage Liver Disease (MELD), the albumin–bilirubin (ALBI) score, and biomarkers such as alpha-fetoprotein (AFP)." (PMID 38396445, 2024). "The study identified AKT1, EGFR, ALB, and TNF genes as potential therapeutic targets against hepatic cancer." (PMID 39502516, 2024). "We compared age, sex, etiology, Child–Pugh score, platelet count, albumin, total bilirubin, prothrombin time, ALBI score, tumor size, number of nodules, alpha-fetoprotein, des-γ-carboxy prothrombin, Barcelona Clinic Liver Cancer, and previous TACE." (PMID 36765804, 2023). "The albumin-bilirubin (ALBI) score and Barcelona Clinic Liver Cancer (BCLC) classification were assessed in each case, and all patients were treated accordingly." (PMID 35800821, 2022).